FOXP3 (forkhead box P3)
Diseases named in the same sentence as FOXP3 in open-access papers (continued):
Sharing a sentence is not in itself a finding about the gene and the disease.
tendinopathy (3 papers, 2018 to 2023). "The combined analysis of FCRL3 –169T>C and FOXP3 –2383C>T suggested a gene-gene interaction in the susceptibility to tendinopathy." (PMID 30021560, 2018). "The main aim of this study was to investigate the contribution of FCRL3 –169T>C and FOXP3 –2383C>T polymorphisms as risk factors for tendinopathy development in volleyball athletes, as well as their association with tendinopathy symptoms and sports activities." (PMID 30021560, 2018). "The combined variant genotypes, FCRL3 –169TC or –169CC and FOXP3 –2383CT or –2383TT, were associated with an increased risk of tendinopathy among athletes with tendon pain (OR = 2.24; 95% CI: 1.14–4.40 and OR = 2.60; 95% CI: 1.11–6.10)." (PMID 30021560, 2018). "As far as we know, the present study is the first study to focus on the possible contribution of the FCRL3 –169T>C and FOXP3 –2383C>T polymorphisms to the susceptibility to tendinopathy in elite athletes." (PMID 30021560, 2018). "The combined analysis of FCRL3 –169T>C and FOXP3 –2383C>T suggests a gene-gene interaction in the susceptibility to tendinopathy." (PMID 30021560, 2018). "FCRL3 –169T>C and FOXP3 –2383C>T polymorphisms are located near elements that regulate respective genes expression, thus it was deemed relevant to evaluate these polymorphisms as risk factors for tendinopathy development in athletes." (PMID 30021560, 2018). "Furthermore, in present study the combined variant genotypes of FCRL3 –169T>C and FOXP3 –2383C>T were also associated with an increased risk for developing tendinopathy among athletes who presented tendon pain or were away from training due to pain." (PMID 30021560, 2018). "We hypothesized that polymorphisms in FCRL3 and FOXP3 genes may influence the onset and/or the progression of tendinopathy." (PMID 30021560, 2018). "In this study, FCRL3 and FOXP3 polymorphisms and male gender were associated with a moderate risk (approximate 2-fold), whereas athlete older age and higher years of practice in volleyball were associated with a higher risk (approximate 8-fold) of tendinopathy." (PMID 30021560, 2018). "Moreover, a combined analysis of the FCRL3 –169T>C and FOXP3 –2383C>T polymorphisms was performed to investigate if their interaction would increase the risk of developing of tendinopathy among athletes who present tendon pain or were away from training due pain." (PMID 30021560, 2018). "Furthermore, gene variants of FOXP3, FCRL3, BMP4, and FGF3 and FGF10 as well as FGFR1 were analyzed in connection with tendinopathy in competitive athletes." (PMID 34366884, 2021).
tuberculoid leprosy (3 papers, 2014 to 2023). A principal or polar form of leprosy in which the skin lesions are few and are sharply demarcated. "Varied results were also reported where increase in FOXP3+ cells was associated with tuberculoid leprosy using flow cytometry analysis." (PMID 24454972, 2014).
ZIKV infection (3 papers, 2017 to 2020). "In vitro, we found that ZIKV infection reduced Foxp3 expression in EL‐4 cells, as well as Smad4 in addition to the reduced phosphorylation of Smad2 and Smad3." (PMID 32057179, 2020). "We showed that overexpression of Smad2 significantly enhanced P‐Smad2 as well as Foxp3 expression level, and ZIKV infection still significantly reduced level of P‐Smad2, P‐Smad3, Smad4 and Foxp3." (PMID 32057179, 2020). "Overexpression of Smad4 exerted no influence on P‐Smad2 and P‐Smad3 expression, but significantly increased Smad4 and Foxp3 expression, ZIKV infection still significantly reduced P‐Smad2, P‐Smad3, Smad4 and Foxp3 expression." (PMID 32057179, 2020). "ZIKV infection led to a significant decrease in the percentage of splenic FoxP3+ Tregs, although this was accompanied by a significant increase in the total number of Tregs present in the spleen." (PMID 28231312, 2017). "We showed that ZIKV infection could directly down‐regulate Foxp3 protein expression." (PMID 32057179, 2020). "We demonstrated that ZIKV infection via the RO and IVag routes generates IL-10-producing Th1 cells, which also possess regulatory activity but are distinct from the CD25+FoxP3+ subset that develops in the thymus." (PMID 30677097, 2019). "However, compared to ZIKV infection in mock transfection (no Smad4 overexpression), overexpression of Smad4 remarkably up‐regulated Smad4 and Foxp3 expression." (PMID 32057179, 2020). "However, compared to ZIKV infection in mock transfection (no Smad2 overexpression), overexpression of Smad2 significantly increased level of Smad3, P‐Smad3, Smad4 and Foxp3." (PMID 32057179, 2020).
acne (2 papers, 2014 to 2024). An inflammatory process of the sebaceous glands which is characterized by comedones, nodules, papules and/or pustules on the skin. "Retinoids exert beneficial effects on acne, via inhibition of IL-17 and increase in Foxp3 expression, whereby regulating the balance between Treg and Th17 cell differentiation." (PMID 38357543, 2024). "Significantly high numbers of Foxp3+ cells are observed in the papillary dermis in early acne lesions." (PMID 38357543, 2024). "In the German cohort, TGF-β and IL-10 displayed a slightly enhanced expression in acne lesions and also the expression of Foxp3 was detected." (PMID 25153527, 2014). "Retinoic acid can regulate reciprocally Tregs and Th17 via TGF-β -dependent generation of Foxp3, a mechanism that may be of importance in the treatment of acne by isotretinoin." (PMID 25153527, 2014). "In the Finnish cohort, the expression of Foxp3, TGF-β and IL-10 were found significantly up-regulated in acne lesions by RT-PCR, and the latter two were at higher levels in acne lesions compared with psoriatic lesions." (PMID 25153527, 2014). "Yet, the number of Foxp3+ cells was significantly higher in the acne lesions in the papillary dermis but not around follicles." (PMID 25153527, 2014). "We defined the markers of T cell subsets at mRNA level and studied Th1 (T-bet), Th17 (IL-17A), Treg (Foxp3) cells, cytotoxic CD8+ T-cells and CD68 macrophages and CD83 positive activated dendritic cells in clinically early acne lesions by immunohistochemistry both phenotypically and proportionally." (PMID 25153527, 2014).
acute pancreatitis (2 papers, 2018 to 2022). An acute inflammatory process that leads to necrosis of the pancreatic parenchyma. "One study showed that human clonal BM-MSCs suppressed T cell proliferation and increased the expression of Foxp3 regulatory T cells in pancreatic tissue with mild or severe acute pancreatitis." (PMID 29743979, 2018). "However, rats in the severe acute pancreatitis + butyrate group showed markedly increased expressions of Foxp3 and GPR109a and the upregulated percentage of Treg cells (P < .01)." (PMID 35943149, 2022). "In addition, rats in the severe acute pancreatitis group showed the obvious reduction in the expressions of Foxp3 and GPR109a and the decreased percentage of Treg cells in the intestine (P < .001) compared to rats in the control." (PMID 35943149, 2022).
Addison’s disease (2 papers, 2012 to 2025). "Our in vitro observations support the idea of a negative regulation of the FoxP3 transcription factor by DHEA, which was also seen in cells from Addison’s disease patients." (PMID 22431997, 2012). "To date, only a few studies have examined Treg expression and function in patients with primary adrenal insufficiency, reporting either a numerical downregulation of Foxp3+ Tregs or no significant changes in Treg expression." (PMID 40003944, 2025).
African trypanosomiasis (2 papers, 2017 to 2021). "Several reports have shown that CD4+CD25+Foxp3+ Tregs play disease-promoting role in experimental African trypanosomiasis." (PMID 28769924, 2017).
allergic contact dermatitis (2 papers, 2013 to 2016). An inflammatory skin condition caused by an immune response to direct contact between the skin and an allergen. "Indeed, Foxp3 Treg have the capacity to interact with the skin vasculature and to alleviate allergic contact dermatitis by regulating the extravasation of CD8 effector T cells into the skin." (PMID 23922690, 2013). "Heat-killed Lactobacillus acidophilus strain L-92 produced higher levels of Foxp3, IL-10 and TGF-β compared to control mice and suppresses allergic contact dermatitis." (PMID 27175277, 2016).
anal carcinoma (2 papers, 2009 to 2016). "In an anal cancer cohort we studied the spatial distribution of dendritic cells (CD1a+), B cells (CD20) and Treg (FoxP3+) and found most of the dendritic cells and epithelial B cells to be non-functional, while stromal B cells and FoxP3+ cells were presumed to be functional cells." (PMID 27494875, 2016).
anxiety disorder (2 papers, 2016 to 2024). A category of psychiatric disorders which are characterized by anxious feelings or fear often accompanied by physical symptoms associated with anxiety. "State anxiety was negatively associated with the percentage of FoxP3+ Tregs in the parent gate (β = −2.88, p = 0.031) as well as subpopulations of Helios+ (β = −3.29, p = 0.019) and TIM-3+ (β = −3.17, p = 0.008) Treg cells at 12 weeks." (PMID 38016492, 2024). "More specifically, we found that more feelings of perceived stress were associated with lower percentages of the PD-1+ Treg subpopulation and that symptoms of state anxiety were associated with lower percentages FoxP3+ Tregs as well as Helios+ and TIM-3+ subpopulations at 12 weeks.." (PMID 38016492, 2024).
apical periodontitis (2 papers, 2021). "Moreover, the skewed distribution of Th17/Treg cells in the periapical bone region of OVX/periapical periodontitis rats was also rescued by the treatment of probiotics, as reflected by decreased number of IL‐17A+ cells and increased number of Foxp3+ cells per hpf." (PMID 34101283, 2021). "In mice, the expression of VISTA gradually increased with the development of mouse experimental apical periodontitis (MAP), the CD3+ T cells, CD11b+ myeloid cells, and FOXP3+ regulatory T cells also gradually accumulated." (PMID 34691045, 2021).
Atherosclerotic lesion (2 papers, 2020 to 2025). A lesion associated with atherosclerosis, a multifactorial and multipart progressive disease manifested by the focal development within the arterial wall of lesions, that ranges from the development of a fatty streak, plaque progression, and plaque disruption. "Following crosslinking with multi-arm PEG for in situ gelation, aVD-loaded FM-depots maintained high levels of Foxp3+ Tregs in both lymphoid organs and atherosclerotic lesions for weeks following a single subcutaneous injection into ApoE−/− mice." (PMID 32582667, 2020).
atopic asthma (2 papers, 2015 to 2018). An asthma that is characterized by symptoms that are triggered by an allergic reaction caused by inhaled allergens such as dust mite allergen, pet dander, pollen and mold. "We thus concluded that adult atopic asthma patients have an increase of circulating CD4+ T cells that are CD25+, FoxP3+, and CTLA-4+, FoxP3+CD25high, or FoxP3+CTLA-4+." (PMID 29507584, 2018).
B cell deficiency (2 papers, 2021 to 2025). A broad classification of disorders where circulating numbers of B lymphocytes are decreased or ineffective. "Patients with B-cell deficiency also showed concurrent reductions in total T cells, CD4+ T cells, and CD4+CD25+CD127low/FOXP3+ regulatory T cells (Tregs)." (PMID 41141591, 2025).
Behcet disease (2 papers, 2015 to 2017). A chronic, relapsing, multisystemic vasculitis characterized by mucocutaneous lesions, as well as articular, vascular, ocular and central nervous system manifestations. "This study aimed to investigate the role of genetic variants including single nucleotide polymorphisms (SNPs) and copy number variants (CNVs) of TBX21, GATA3, Rorc and Foxp3 genes in Behcet's disease (BD) and Vogt-Koyanagi-Harada (VKH) syndrome in a Chinese Han population." (PMID 25873156, 2015).
Bladder Urothelial Carcinoma (2 papers, 2022 to 2024). "Previously, we have shown the clinical correlation of FOXP3 expression to worse overall survival in patients with urothelial bladder cancer as well as the induction of genes that mediate cancer cell differentiation and chemotherapy resistance." (PMID 39099201, 2024).
brucellosis (2 papers, 2019 to 2021). Brucellosis is a bacterial infection that spreads from animals to people via unpasteurized dairy products or by exposure to contaminated animal products or infected animals. "Few studies have described the association between Foxp3+ Tregs and patients with brucellosis." (PMID 34592958, 2021). "Similarly, human clinical studies have demonstrated an increased frequency of FoxP3+ Tregs in the peripheral blood of patients with brucellosis." (PMID 34592958, 2021). "After the third course of treatment (about 80 days), the frequency of Foxp3+ Tregs in the PBMCs of acute brucellosis patients decreased to normal level of healthy individuals, while the frequency of Foxp3+ Tregs in immune enhancing treatment patients remained higher." (PMID 31636897, 2019).
carcinoma in situ (2 papers, 2022 to 2024). "Among CD4+ T cells, the percentage of GATA3+FOXP3– cells and the percentage of GATA3+FOXP3+ cells were higher in invasive melanoma compared with in situ melanoma, while the percentage of GATA3–FOXP3+ cells remained similar." (PMID 36107619, 2022).
cerebral malaria (2 papers, 2020 to 2026). A sequestration of Plasmodium falciparum in the brain, which can cause coma and/or seizures. "In an experimental cerebral malaria study, the induction of IL-33 has led to the polarization to the pro-resolutive macrophages of M2 phenotype and forkhead box P3 (Foxp3) Treg cells." (PMID 32599864, 2020).
cervical adenocarcinoma (2 papers, 2015 to 2025). An adenocarcinoma arising from the cervical epithelium. "In addition, other studies have shown that in cervical adenocarcinomas, the FOXP3+ Tregs may have beneficial effects and be associated with a better prognosis." (PMID 41007768, 2025).
cervical disease (2 papers, 2014 to 2021). "One manuscript which was not suitable for meta-analysis reported a significant trend towards increasing FoxP3 infiltration with increasing severity of cervical disease." (PMID 33257839, 2021). "The protein expression levels of Foxp3 and IL-10 increased along with the progression of pathology of cervical disease." (PMID 24837834, 2014).
chronic asthma (2 papers, 2014 to 2015). An asthma that is characterized by the development of persistent airway inflammation and recurrent attacks of breathlessness and wheezing, which vary in severity and frequency. "We found that in BAL fluid of patients with chronic asthma have a decreased population of CD4+Foxp3+TGF-β+ cells and at the same time an increased population of CD4+IL-17+ cells, CD4+IL-17+ IFN-γ+ cells and CD4+IL-4+ cells." (PMID 25132806, 2014). "Our results suggest that in the airways of chronic asthma patients there is an imbalance between increased numbers of CD4+IL-17+ cells and Th2 cells and decreased number of CD4+Foxp3+TGF-β+." (PMID 25132806, 2014). "In conclusion, our results suggest that in the airways of chronic asthma patients there is an imbalance between the increased population of CD4+IL-17+ cells, CD4+IL-17+IFN-γ+ cells and CD4+IL-4+ cells and the decreased population of CD4+Foxp3+TGF-β+ cells." (PMID 25132806, 2014).
chronic granulomatous disease (2 papers, 2015 to 2019). Chronic granulomatous disease (CGD) is a rare primary immunodeficiency, mainly affecting phagocytes, which is characterized by an increased susceptibility to severe and recurrent bacterial and fungal infections, along with the development of granulomas. "This was confirmed using macrophages from patients with chronic granulomatous disease (CGD) that are defective in ROS production; CGD macrophages allowed significantly more T cell activation and expansion and induced fewer FOXP3+ cells than did macrophages from control subjects." (PMID 26635790, 2015).
chronic heart failure (2 papers, 2019 to 2024). "The level of Foxp3 was significantly lower in chronic heart failure patients with ischemic etiology versus non-ischemic one in the mentioned study." (PMID 31384408, 2019).
Chronic myeloid leukemia (2 papers, 2019 to 2022). "In the bone marrow of newly diagnosed chronic myeloid leukemia patients, TNFRSF4 mRNA levels were dramatically raised and linked with the expression of the Treg-restricted transcription factor FOXP3." (PMID 36100891, 2022).
classic Hodgkin lymphoma (2 papers, 2018 to 2020). Classical Hodgkin lymphoma (CHL) is a B-cell lymphoma characterized histologically by the presence of large mononuclear Hodgkin cells and multinucleated Reed-Sternberg (HRS) cells. "Expression of forkhead box P3 (FOXP3), a key regulator of T-cell function, in the tumor immune microenvironment is related to survival in classic Hodgkin lymphoma (CHL)." (PMID 32513132, 2020).
colorectal adenoma (2 papers, 2020 to 2025). An adenoma that arises from the colon or rectum. "We examined the correlation between ST2 cell expression and FoxP3 positive Tregs in both colorectal adenoma and cancer (CRC) microenvironment by real-time PCR, immunohistochemistry (IHC) and double immunofluorescences." (PMID 32246094, 2020). "We recently reported that the increase of FoxP3-positive Tregs is accompanied by the increased expression of the immunosuppressive cytokine IL-10 along the human colorectal adenoma-carcinoma sequence." (PMID 32246094, 2020). "Our review shows a gradual increase in FOXP3+ Tregs in CR lesions along the conventional ACS, with a slight rise in colorectal adenoma and a more significant increase in carcinoma tissues." (PMID 40149674, 2025).
dermatomyositis (2 papers, 2014 to 2016). Dermatomyositis (DM) is a type of idiopathic inflammatory myopathy characterized by evocative skin lesions and symmetrical proximal muscle weakness. "In studies describing Treg numbers in adults with systemic sclerosis or dermatomyositis, contrasting results have been found and it remains unclear whether FOXP3 expressing Tregs are present and functional in JDM patients." (PMID 25157414, 2014).
digestive (2 papers, 2021 to 2024). "This study investigates the effect of intraoperative blood transfusion on the number of Tregs and the expression of FOXP3 in the blood of patients with different ABO blood types and digestive tract malignancies." (PMID 33838641, 2021).
E. coli infection (2 papers, 2013 to 2024). "The results demonstrated that baicalin supplementation counteracted the increase in the proportion of CD3+ cells and Foxp3+ cells caused by E. coli infection." (PMID 39707535, 2024). "We found that percentages of CD4+CD25+Foxp3+ Tregs in CD4+ PTLN cells were significantly elevated by E. coli infection, along with the enhanced IL-10 secretion." (PMID 23536867, 2013). "Subsequent flow cytometry analysis showed that E. coli infection increased the numbers of CD3+ and Foxp3+ cells, decreased IL-17A+ cells, and reduced Th17/Treg ratios." (PMID 39707535, 2024).
endotoxemia (2 papers, 2012 to 2015). "In our model of endotoxemia, application of homogenized AFS cells significantly increased the population of CD4+CD25+Foxp3+ regulatory T cells 24 h after endotoxemic challenge, whereas vital AFS cells only tended to show these effects." (PMID 22539976, 2012).